INHA (inhibin subunit alpha)
Diseases named in the same sentence as INHA in open-access papers (continued):
Sharing a sentence is not in itself a finding about the gene and the disease.
breast carcinoma (4 papers, 2021 to 2024). "In Luminal A breast cancers, we observed that increased INHA expression was associated with unresponsiveness to chemotherapy while in survival data it was a positive predictor of survival." (PMID 33819300, 2021). "Analysis of breast cancer data revealed a similar trend as INHA expression was significantly correlated (r = 0.2026, p = 0.0165) with the Winter hypoxia score (Fig. 2diii)." (PMID 35654828, 2022). "Interestingly, examining expression revealed that in the same luminal A breast cancers INHA, ENG and INHBA are less expressed in responders to pharmacological treatment while TGFBR3 is more expressed in these responder groups." (PMID 33819300, 2021). "Previously, FSRH, INHA, ESR1, and BMP15 gene polymorphisms have been studied with regard to the conditions of the female reproductive system, including polycystic ovary syndrome, poor ovarian response, POI, breast cancer, and endometriosis, as well as male infertility." (PMID 37239044, 2023). "INHA, INHBA, TGFBR3, and ENG also predicted patients’ response to anthracycline and taxane therapy in luminal A breast cancers." (PMID 33819300, 2021). "We next examined individual genes and find that in luminal A breast cancers ENG, TGFBR3, INHA, and INHBA, were better performing as compared to INHBB particularly for taxane or anthracycline based chemotherapy regimens." (PMID 33819300, 2021). "In summary INHA, INHBA, TGFBR3, and ENG display clear discrepant profiles of expression among responders and non-responders to both anthracycline and taxane chemotherapy for distinct breast cancer subtypes, specifically luminal A, and serous ovarian cancer." (PMID 33819300, 2021).
lung carcinoma (4 papers, 2020 to 2021). "Additionally, in lung cancers, INHA and ENG differed from TGFBR3, as INHA (HR = 1.26, p = 0.00029) and ENG (HR = 1.20, p = 0.0056) were both negative predictors of survival while TGFBR3 (HR = 0.65, p = 3.4E-7) was a strong positive predictor of survival." (PMID 33819300, 2021). "For other IRGs, such as LGR4, GDF10, GREM1, IL20RB, INHA, VIPR1, and ADM2, they had been verified to participate in carcinogenesis and affect patients’ prognoses in other cancers, although the relevant studies were rare in lung cancer." (PMID 33386920, 2021). "The remaining six genes (IGKV4‐1, IGKV6D‐41, TNFRSF11A, INHA, IL11 and SCH3) have not been reported in the literature and may be used as potential biomarkers for lung cancer research." (PMID 32686362, 2020).
ovarian carcinoma (4 papers, 2014 to 2022). A malignant neoplasm originating from the surface ovarian epithelium. "A strong expression of INHA in tumor adjacent stroma cells observed in a fraction of otherwise INHA-negative ovarian carcinomas would also be consistent with the paracrine stimulation of tumor cell growth." (PMID 36289769, 2022). "Using these signatures, inhibinα (INHA) expression was significantly correlated with both hypoxia Buffa (r = 0.1961, p = 0.0221) and Winter hypoxia (r = 0.223, p = 0.009) scores in the ovarian cancer data set (Fig. 2di–ii)." (PMID 35654828, 2022). "A mouse ovarian cancer cell line, ID8ip2, was also tested and INHA expression was elevated 4-times here as well." (PMID 35654828, 2022). "To determine the roles of the HIF-1 and HIF-2 heterodimeric transcriptions factors, that both require ARNT37, in the transcriptional regulation of INHA we used siRNA to knockdown the levels of HIF-1α and HIF-2α in two ovarian cancer cell lines (OV90 and HEY)." (PMID 35654828, 2022). "As the effect of forskolin was additive on INHA expression, cAMP and PKA could represent an alternative or additive mechanism of regulation of INHA in ovarian cancer." (PMID 35654828, 2022).
ovarian tumors (4 papers, 2013 to 2021). "Recent studies have implicated that the function of INHA is linked with androgen-independent metastasis of prostate cancer and angiogenesis of ovarian tumor." (PMID 34612148, 2021). "Unexpectedly, we found that constitutive activation of TGFBR1 using GLI-Kruppel family member GLI1 (Gli1)-CreERT2 (designated as TGFBR1-CAGcre) caused the development of INHA-positive ovarian tumors following tamoxifen injection." (PMID 27344183, 2016). "By performing histological and molecular analyses, we demonstrated that the ovarian neoplasms were sex cord-stromal tumors which expressed granulosa cell markers including FOXL2, INHA, and FOXO1." (PMID 29221447, 2017). "We found that ovarian tumors from TGFBR1-CAAcre mice were immunoreactive for FOXL2, FOXO1, and INHA, supporting the development of granulosa cell tumors in these mice." (PMID 27344183, 2016). "To define the molecular characteristics of ovarian tumors in TGFBR1-CAG9Cre mice, we performed immunostaining to examine the expression of a granulosa cell lineage marker FOXL2 and three other granulosa cell-expressed proteins, FOXO1, INHA, and AMH." (PMID 29221447, 2017). "The localization of FOXL2, INHA, FOXO1, AMH, and DDX4 was detected in the granulosa cell or oocyte compartment of control ovaries, while ovarian tumor tissues from TGFBR1-CAG9Cre mice were immunoreactive with FOXL2, INHA, and FOXO1, supporting the development of GCTs in these mice." (PMID 29221447, 2017).
granulosa cell tumor (3 papers, 2016 to 2023). A slow-growing, malignant tumor, characterize by the presence of granulosa-like cells and Call-Exner bodies, that is almost always found in the ovary. "To further determine the molecular identity of tumors observed in TGFBR1CA; Amh-Cre mice, we conducted immunostaining using antibodies against three granulosa cell tumor-expressed protein markers including FOXL2, INHA, and FOXO1." (PMID 38067144, 2023). "At an early age, these mice demonstrated follicular defects and development of ovarian granulosa cell tumors, which were immunoreactive for granulosa cell markers including FOXL2, FOXO1, and INHA." (PMID 29221447, 2017).
lung adenocarcinoma (3 papers, 2020 to 2022). A carcinoma that arises from the lung and is characterized by the presence of malignant glandular epithelial cells. "Other tumor entities which can show high-level INHA expression include, for example, neuroendocrine tumors of the pancreas, cholangiocarcinoma, adenocarcinoma of the lung, gastric adenocarcinoma, and clear cell renal cell carcinoma." (PMID 36289769, 2022). "Exceptions were head and neck and esophagogastric cancers that had high expression of INHBA and lung adenocarcinoma and renal clear cell carcinoma that had high expression of INHA." (PMID 33819300, 2021). "Our results showed that INHA was a marker of poor prognosis in lung adenocarcinoma." (PMID 33072571, 2020). "Finally, hub IRGs CLEC17A, INHA, and XIRP1 were considered novel prognostic biomarkers for lung adenocarcinoma." (PMID 33072571, 2020). "However, INHA remained a robust negative predictor of survival in lung adenocarcinomas patients expressing low ENG (HR = 2.12, p = 0.00041) but was not significant in ENG high expressing patients (HR = 1.25, p = 0.14)." (PMID 33819300, 2021). "Similar outcomes were observed in lung adenocarcinomas with respect to TGFBR3, where INHA remained a strong negative predictor of survival in patients regardless of TGFBR3 expression levels." (PMID 33819300, 2021). "Specifically, we find that INHA and ENG are robust predictors of poor survival in lung adenocarcinomas but not in squamous cell carcinomas." (PMID 33819300, 2021).
male infertility (3 papers, 2021 to 2023). The inability of the male to effect fertilization of an ovum after a specified period of unprotected intercourse. "Previous studies have found that a large number of INHA gene mutations are closely related to reproductive system problems such as male infertility, premature ovarian failure, superovulation, follicular cysts, and sperm quality." (PMID 37187517, 2023). "The c.-124 G > A polymorphism of the INHA gene promoter region may cause male infertility in Pakistani." (PMID 34612148, 2021). "INHA rs11893842 and rs35119453 are located in the promoter region of the INHA gene and have been studied with regard to POI, male infertility (sperm parameters), and adrenocortical cancer." (PMID 37239044, 2023).
ovarian failure (3 papers, 2012 to 2017). "However, it is not possible to exclude the involvement of autosomal genes in the onset of ovarian insufficiency as some genes located on autosomes have been associated with the POF phenotype, for example INHA, FSHR and FOXL2." (PMID 22794123, 2012).
Parkinson disease (3 papers, 2009 to 2012). A progressive degenerative disorder of the central nervous system characterized by loss of dopamine producing neurons in the substantia nigra and the presence of Lewy bodies in the substantia nigra and locus coeruleus. "Both an in vitro bacterial growth study and an enzyme kinetic assay supported our previous in silico prediction that Comtan, a drug used in the treatment of Parkinson's disease, could potentially be repurposed to target InhA directly." (PMID 21079673, 2010). "Since rifampin inhibits DNA-dependent RNA polymerase, this observation implies cross-reactivity between the M.tuberculosis InhA, the target of isoniazid, and the drug targets of Parkinson's disease, which is consistent with our predictions that InhA inhibitors can also inhibit COMT." (PMID 19578428, 2009). "From this result, entacapone, a drug already approved to treat Parkinson's by inhibiting COMT, was predicted to bind to InhA, which was then validated biochemically and shown to have antibacterial activity." (PMID 23300409, 2012). "The similarity between a drug target for Parkinson's disease, catchol-O-methyltransferase (COMT) and a bacterial protein in Mycobaterium tuberculosis (the enoyl-acyl carrier protein reductase, InhA) narrowed down an investigation of potential drug targets for M. tuberculosis infections." (PMID 23300409, 2012).
polycystic ovary syndrome (3 papers, 2019 to 2023). A disorder that manifests as multiple cysts on the ovaries. "In the clinics, both AMH and INHA are used as markers to diagnose polycystic ovary syndrome (PCOS), and the sensitivity reached 96.2% when both AMH and INH are detected in combination, indicating that AMH and INHA may have complementary roles in abnormal ovarian function." (PMID 34820437, 2021).
premature ovarian failure (3 papers, 2010 to 2023). "For example, the human gene inhibin alpha (INHA) has been associated with premature ovarian failure, and shows mouse phenotypes of abnormal ovarian follicle morphology, female infertility, and ovarian hemorrhage, among other phenotypes relevant to human disease." (PMID 20092628, 2010). "We examined SNPs in FSHR, INHA, ESR1, and BMP15, which have been associated with primary ovarian failure." (PMID 37239044, 2023). "The occurrence of FSHR, INHA, ESR1, and BMP15 gene polymorphisms has also been reported to be associated with various reproductive diseases, including primary ovarian insufficiency (POI), pregnancy loss, and preeclampsia." (PMID 37239044, 2023).
adenoma (2 papers, 2014 to 2022). A neoplasm arising from the epithelium. "INHA mRNA expression levels were measured in normal adrenal (n = 10), adrenocortical hyperplasia (n = 20), adenoma (ADA, n = 11) and ACC (n = 25) tissues." (PMID 25111790, 2014).
Adrenocortical Cancer (2 papers, 2014 to 2023). "Furthermore, rs11893842 minor alleles showed a low frequency in adrenocortical cancer patients and the rs11893842 AA genotype was associated with decreased INHA mRNA levels." (PMID 37239044, 2023).
adrenocortical tumors (2 papers, 2021 to 2022).
anthrax (2 papers, 2011 to 2024). "Bacteria-secreted metalloproteases can disrupt host BBB integrity, e.g., Bacillus anthracis InhA contributes to BBB disruption associated with anthrax meningitis through proteolytic attack of the endothelial tight junctional protein zonula occludens (ZO)-1." (PMID 38594770, 2024). "In conclusion, we report here that InhA-induced BBB disruption provides a mechanistic model relevant to anthrax meningitis." (PMID 21437287, 2011). "Although the detailed mechanism of anthrax meningitis remains to be elucidated, available data allow us to suggest that the effect of InhA on the brain may have relevance to its capacity to induce thrombosis and blood coagulation." (PMID 21437287, 2011). "However, a possible role for InhA in development of anthrax meningitis has not been demonstrated." (PMID 21437287, 2011).
Azoospermia (2 papers, 2022 to 2024). Absence of any measurable level of sperm,whereby spermatozoa cannot be observed even after centrifugation of the semen pellet. "We have observed azoospermia and infertility in our patients with homozygous INHA mutations." (PMID 35235537, 2022). "A homozygous 2 bp deletion c.208_209delAG, p.(R70Gfs*3) in the INHA gene was found in two brothers with hypospadias, hypergonadotropic hypogonadism, gynecomastia, and azoospermia." (PMID 39337600, 2024).
clear cell renal cell carcinoma (2 papers, 2021 to 2022). "Due to the rareness of immunohistochemically detectable INHA expression in most cancer types, we were only able to compare INHA immunostaining data with available clinical data in neuroendocrine tumors, clear cell renal cell carcinoma, and colorectal adenocarcinoma." (PMID 36289769, 2022). "Interestingly, this trend was also repeated in renal clear cell carcinoma, where INHA was only a predictor of survival in TGFBR3 low (HR = 2.75, p = 9.0E-06) and ENG low (HR = 2.6, p = 2.5E-06)." (PMID 33819300, 2021). "The ability of renal carcinomas to highly express INHA is of particular relevance because INHA immunohistochemistry is used as a tool to distinguish normal or neoplastic adrenal tissue from clear cell renal cell carcinomas, as these entities may be difficult to distinguish by morphology alone." (PMID 36289769, 2022). "In highly angiogenic tumors like renal clear cell carcinoma and glioblastoma, we found INHA expression to be a significant negative predictor of survival." (PMID 33819300, 2021).
diabetes (2 papers, 2022 to 2024). "According to the literature, only the INHA and NR1H2 genes are involved in steroidogenesis, sex development, and/or reproduction, while the other genes are either involved in diabetes or cancer." (PMID 39337600, 2024).
Follicular Cyst (2 papers, 2019 to 2023). Cyst due to the occlusion of the duct of a follicle or small gland. "In some studies, polymorphisms in the INHA gene have been found to be significantly associated with follicular cysts in humans, pigs, and other mammals." (PMID 31485447, 2019).
Gynecomastia (2 papers, 2022 to 2024). Abnormal development of large mammary glands in males resulting in breast enlargement. "Both patients with INHA mutations exhibited significant gynecomastia." (PMID 35235537, 2022).
hypospadias (2 papers, 2022 to 2024). Hypospadias is the displacement of the urethral meatus on the ventrum of the penis. "This is the first report of male patients presenting with hypospadias, primary testicular failure, and infertility due to homozygous INHA mutations." (PMID 35235537, 2022). "However, both patients with INHA mutations had hypospadias and did not have testicular tumours, suggesting that androgen deficiency exists prenatally and impairs the hormone-dependent stage of external genitalia development in males." (PMID 35235537, 2022).
melanoma (2 papers, 2021). A malignant, usually aggressive tumor composed of atypical, neoplastic melanocytes. "Western blot analysis showed that INHA expression was only downregulated in melanoma cells infected with S. Typhimurium expressing the INHA miRNA vector." (PMID 34835533, 2021). "The result demonstrated that CCLB (P = 0.018), INHA (P < 0.001), and NDRG1 (P = 0.001) were significantly upregulated in metastatic melanoma, while LHB (P = 0.001) was significantly downregulated when compared with primary melanoma." (PMID 33688507, 2021).
meningitis (2 papers, 2011 to 2024). A disorder characterized by acute inflammation of the meninges of the brain and/or spinal cord. "Experiments with mice challenged with purified InhA or vegetative bacteria of the ΔinhA strain of B. anthracis indicate that expression of InhA contributes to hemorrhagic brain damage associated with fatal meningitis." (PMID 21437287, 2011). "Microscopic analysis of the brain sections confirmed that InhA is required for the development of meningitis." (PMID 21437287, 2011). "Collectively, these data demonstrate that InhA is involved in breaching the BBB and hemorrhagic brain damage contributing to the development of meningitis and B. anthracis virulence." (PMID 21437287, 2011).
Multidrug resistant TB (2 papers, 2013 to 2020). "Multidrug resistant TB (MDR-TB), defined as resistance to at least RIF and INH, is usually caused by MTBC strains that harbour mutations in rpoB, katG and inhA genes associated with RIF and INH resistance." (PMID 32085703, 2020).
prostate carcinoma (2 papers, 2021). A carcinoma that arises from epithelial cells of the prostate gland. "INHA’s role in promoting tumorigenesis in these cancer types may occur through its effects on angiogenesis as has been previously reported for a subset of ovarian and prostate cancer warranting further investigation." (PMID 33819300, 2021).
brain cancer (1 paper, 2021). A primary or metastatic malignant neoplasm affecting the brain. "Finally, in brain cancers, INHA was a negative predictor of survival in glioblastoma but a positive predictor in low-grade gliomas." (PMID 33819300, 2021).
cholesteatoma (1 paper, 2023). A pathologic process characterized by the proliferation of keratinizing squamous epithelium resulting in the accumulation of keratin and cells in the middle ear and/or mastoid. "The results showed that INHBA was significantly upregulated relative to INHBB and INHA in cholesteatoma fibroblasts." (PMID 37537159, 2023). "To elucidate the expression of INHBA, INHBB, and INHA in cholesteatoma mouse model fibroblasts, we collected fibroblasts from the cholesteatoma mouse model and control mouse ear pinnae via cell sorting." (PMID 37537159, 2023). "Therefore, we compared the expression patterns of INHBA, INHBB, and INHA in human cholesteatoma fibroblasts by ddPCR." (PMID 37537159, 2023).
endometrial adenocarcinoma (1 paper, 2022). "Cysteine mutations in TGFB2, INHA, and INHBB associated with endometrial adenocarcinoma plus cysteine mutations in TGFB2 and TGFB3 with Loeys–Dietz syndrome lead to the hypothesis that TGFB2 is capable of heterodimerization with numerous partners." (PMID 36214621, 2022).
endometrial tumor (1 paper, 2022). "The fact that TGFB2 shares 2 β8 cysteines and an endometrial adenoma phenotype with INHA and INHBB implies that TGFB2 can heterodimerize with either to prevent endometrial tumor formation." (PMID 36214621, 2022).